FGFR1 (fibroblast growth factor receptor 1)
Diseases named in the same sentence as FGFR1 in open-access papers (continued):
Sharing a sentence is not in itself a finding about the gene and the disease.
Hepatic steatosis (11 papers, 2012 to 2026). Steatosis is a term used to denote lipid accumulation within hepatocytes. "Flux of free fatty acids and adipokines from adipocytes regulated by FGFR1 in turn communicates back to liver to limit hepatic lipogenic gene expression and extent of hepatic steatosis and associated stress." (PMID 23106963, 2012). "To uncover the mechanisms underlying the improvement in hepatic steatosis by a KD, we performed RNA-Seq analysis on mouse livers and found that the mRNA expression profile of Fgf21 signaling was significantly upregulated, especially Fgf21, Klb, and Fgfr1." (PMID 38609395, 2024). "Data from experimental studies have shown that FGF-21, acting through on its receptor (FGFR1) on the cell membrane with β-Klotho as co-receptor, increases fatty acid β-oxidation and decreases de novo lipogenesis, thereby attenuating hepatic steatosis." (PMID 40465044, 2025). "Adipocyte-specific deletion of FGFR1 aggravates hepatic steatosis, indicating the plausible FGFR1 regulation on maintenance of energy homeostasis across multiple organs." (PMID 35983184, 2022). "This communication primarily governed by adipose FGFR1 serves to limit adipose lipolysis and hepatic steatosis, liver stress and resultant damage under stressful or adverse conditions." (PMID 23106963, 2012). "Although the liver FGFR4 is silenced, the beneficial effects of FGF15/19 on liver steatosis may be due to its action via FGFR4 in the intestine or FGFR1 in the liver or adipose tissue." (PMID 36586437, 2023). "The deficit of adipocyte FGFR1 increased the severity of the hepatic steatosis." (PMID 23106963, 2012). "Starvation conditions precipitated a concurrent elevation of serum triglycerides and non-esterified fatty acids, and increased hepatic steatosis and adipose lipolysis in the FGFR1-deficient mice." (PMID 23106963, 2012). "These starvation-dependent observations on serum parameters elicited by the adipocyte FGFR1 deficiency are consistent with the general elevation of specifically hepatic lipogenic genes and hepatic steatosis, without effect on hepatic genes involved in glucose and ketone body metabolism." (PMID 23106963, 2012). "Overall, PAC alleviates hepatic steatosis in NAFLD by enhancing FGF21 expression, activating the FGF21/FGFR1 signaling axis, and inhibiting p38MAPK activation." (PMID 42100018, 2026). "It has been found to reduce fatty liver disease and steatohepatitis, a disorder of lipid metabolism in non-alcoholic fatty liver disease mice, through upward regulation of the FGF21/FGFR1 pathway." (PMID 37958806, 2023). "The levels of miR-22 are inversely correlated with those of FGF21 and FGFR1 in human and mouse fatty livers, and miR-22 inhibition reduces hepatic steatosis via FGF21 and FGFR1 induction." (PMID 33664851, 2021).
holoprosencephaly (11 papers, 2015 to 2025). Holoprosencephaly (HPE) is a complex brain malformation resulting from incomplete cleavage of the prosencephalon, occurring between the 18th and 28th day of gestation, and affecting both the forebrain and face, which results in neurological manifestations and facial anomalies of variable severity. "Other gene mutations that relates to holoprosencephaly, including ZIC2, SIX3, TGIF1, CDON, FGFR1, CENPF and DHCR7, were not identified." (PMID 39859210, 2025).
liver cancer (11 papers, 2011 to 2023). An epithelial or non-epithelial malignant neoplasm that arises from the liver. "The inhibitory activity of LD1 was characterized using liver cancer cell lines with various levels of endogenous FGFR (i.e. FGFR1-4) expression." (PMID 22615798, 2012). "We used Western blot and flow cytometric and immunocytochemical analyses to investigate the regulation of FGFR1 expression by interferon-α/β in several human hepatic cancer cell lines." (PMID 21573021, 2011). "In liver cancer, no mutation of the FGFR1 gene was found on the TCGA database (cBioPortal database)." (PMID 27384874, 2016). "In clinical practice, several makers of liver cancer, such as VEGFR1, FGFR1 and PDGFRα, were identified and their potentials as a therapeutic target were explored." (PMID 38192337, 2023). "Further explorations show that an adenylate kinase, hCINAP, promotes FGFR1-catalyzed LDHA Y10 phosphorylation in CRC and an lncRNA, HULC, modulates the phosphorylation of LDHA Y10 through FGFR1, elevating aerobic glycolysis of liver cancer cells." (PMID 36407005, 2022). "A cohort of 65 stable liver cancer PDX models were established and revealed that lenvatinib, a FGFR1 inhibitor, presentated better therapeutic effect than sorafenib in the models expressing high levels of FGFR1 gene." (PMID 29743053, 2018).
lymph node metastasis (11 papers, 2015 to 2025). "Similar to FGFR1 amplification, FGFR1 protein overexpression was associated with lymph node metastasis and advanced TNM tumor stages." (PMID 32326908, 2020). "Considering the clinical implications of FGFR1 amplification, we observed significant association with poor prognostic factors, specifically, lymphovascular invasion and advanced stages of lymph node metastasis." (PMID 32326908, 2020). "Overexpression of FGFR1 is linked to lymph node metastasis and poor survival outcomes in LSC." (PMID 40231252, 2025). "FGFR1 amplification observed in 8 (8/66, 12.1%; 6 hypopharynx and 2 larynx) patients and high FGFR1 expression in 21 (21/199, 10.6%) patients significantly correlated with lymph node metastasis and advanced pathological stages." (PMID 32326908, 2020). "FGFR1 amplification status correlated with clinical stage (P=0.047), lymph node metastasis (P=0.032), and necrosis (P=0.008)." (PMID 29088806, 2017). "In DGC, high expression of FGFR1, FGFR2, or FGFR4 was significantly associated with the depth of invasion, lymph-node metastasis, pathological stage, and distant metastasis or recurrent disease." (PMID 28056982, 2017). "Fibroblast growth factor receptor 1 (FGFR1) plays a crucial role in the invasion, metastasis, and causing drug resistance to LSC, and FGFR1 can be an independent prognostic factor for LSC, mainly overexpression of FGFR1 is linked to lymph node metastasis and poor survival outcomes." (PMID 40231252, 2025). "High expression levels of FGFR1, 2, and 4 were significantly associated with the depth of invasion (early cancer vs. advanced cancer), lymph-node metastasis (negative vs. positive), tumor stage (stage I vs. stage II or more advanced), and distant metastasis or recurrence (negative vs. positive)." (PMID 28056982, 2017). "Moreover, FGFR1 amplification of primaries was highly concordant with lymph node metastases (97.7%), so doing a biopsy on metastatic cancer may make sense in order to determine the FGFR1 status of the primary tumor." (PMID 26788508, 2015). "In SQCLC, high FGFR1 protein expression but not amplification was correlated to early clinical stages and to the absence of lymph node metastasis (P = .017 and .019, respectively)." (PMID 32207251, 2020).
cervical carcinoma (10 papers, 2013 to 2025). A carcinoma arising from either the exocervical squamous epithelium or the endocervical glandular epithelium. "Through regulation of the miR377/FGFR1 axis, inhibition of NEAT1 decreased cell survival and migration, and accelerated apoptosis in cervical cancer cells." (PMID 37310654, 2023). "In cervical cancer cells, NEAT1 and FGFR1 expression levels were significantly higher, whereas miR-377 expression was significantly reduced." (PMID 37310654, 2023). "In conclusion, the present study investigated the immunohistochemical expression of FGFR1, FGFR2, FGFR3, and FGFR4 in a large number of cervical cancer patients." (PMID 27154171, 2016). "In the present study, we investigated the prognostic significance of FGFR1, FGFR2, FGFR3, and FGFR4 expression in a large cohort of cervical cancer patients." (PMID 27154171, 2016). "In these abnormal contexts, MIR133b in human cervical carcinoma targets EGFR and FGFR1, similarly acting as a tumor suppressor." (PMID 27471470, 2016). "Thus, the aim of this study is to investigate the clinical significance of FGFR1, FGFR2, FGFR3 and FGFR4 expression in a well-defined cohort of cervical cancers, using immunohistochemistry and quantitative digital image analysis." (PMID 27154171, 2016). "FGFR1, FGFR2, FGFR3, and FGFR4 expression was determined by immunohistochemistry in conjunction with quantitative digital image analysis of 336 formalin-fixed, paraffin-embedded cervical cancer tissues and 61 normal cervical tissues, as well as NCI60 cell microarray." (PMID 27154171, 2016).
diffuse astrocytoma (10 papers, 2016 to 2025). A low-grade (WHO grade II) astrocytic neoplasm. "The second patient had a diffuse astrocytoma grade 2, with an FGFR1 K656E mutation." (PMID 41100064, 2025). "The molecular alterations of these “pediatric-type” grade II diffuse astrocytomas were recently described and concerned the BRAF p.V600E mutation, FGFR1 alterations or MYB or MYBL1 rearrangement." (PMID 32771057, 2020). "Various genetic alterations have been identified in diffuse astrocytomas, including BRAFV600E mutations, intragenic duplication of FGFR1, structural alterations of the MYB oncogene and gene fusions involving FGFR1, FGFR3, MYB and MYBL1." (PMID 27229157, 2016). "FGFR1, NTRK2, MYB, and MYBL1 rearrangements: Among patients with diffuse astrocytomas who had testing for rearrangements of FGFR1 (n = 5), NTRK2 (n = 4), MYB (n = 2), or MYBL1 (n = 1) performed on both paired surgical specimens, results remained negative in all pairs, with no acquisition or loss." (PMID 33153497, 2020). "The FGFR1-ITD has first been reported in 1 case of PA by Jones and coworkers and simultaneously in 13 LGNTs including 2 other PAs, 4 oligoastrocytomas, 3 diffuse astrocytomas, 3 oligodendrogliomas and 1 DNT by Zhang and coworkers." (PMID 27791984, 2017).
type 2 diabetes (10 papers, 2013 to 2024). "Similarly, we observed that SOS2 was another seeder gene that was linked with SRC, INSRR, EGFR, FGFR1, PGFRA and PGFRB gene signatures that were significantly associated with insulin resistance and type 2 diabetes." (PMID 28179884, 2017). "In addition, we recently provided evidence of FGFR1 activation in adipose tissues as a therapeutic target for the treatment of insulin resistance and type 2 diabetes." (PMID 23451204, 2013).
colon carcinoma (9 papers, 2010 to 2024). "In colon carcinomas, receptor mutations are rare, but aberrant splicing causes a decrease in functional FGFR3-IIIb, accompanied by a switch to FGFR1-IIIc." (PMID 20234367, 2010). "In colon cancer cells, after 3 h of exposure to high concentration of curcumin (100 μmol/L), a cDNA microarray analysis showed that levels of MAPK-related genes like MAP3K10 and MAP4K2 and also VEGF and FGFR1 were upregulated." (PMID 34867402, 2021).
Hyperglycemia (9 papers, 2019 to 2025). An increased concentration of glucose in the blood. "It is believed that hyperglycemia-related ROS and H2O2 play a significant role in the mesenchymal activation observed in states deficient in glucocorticoid receptor, SIRT3, or FGFR1." (PMID 40290438, 2025). "Studies showed that long-term HFD-fed obese mice exhibited hyperglycemia, hyperinsulinemia, and hyperlipidemia, with markedly reduced FGFR1 and β-KL expression in adipose tissue." (PMID 35983184, 2022). "Mechanistically, micro-RNA (miR)-21-3p is significantly upregulated in serum from diabetic patients and participates in atrial fibrosis under hyperglycemia conditions by reducing FGFR1 in EAT." (PMID 35983184, 2022). "Our in vitro experimental results also demonstrated that rFGF21 protects against hyperglycemia plus interleukin (IL)-1β-induced transendothelial permeability through upregulation of junction protein expression in an FGFR1 activation and PPARγ activity elevation-dependent manner." (PMID 32012810, 2020). "Our in vitro experimental results demonstrated that rFGF21 is strongly protective in hyperglycemia plus IL-1β -induced transendothelial permeability, which is FGFR1 activation-dependent and PPARγ activity-dependent, and also associated with the maintenance of junction protein expression." (PMID 32012810, 2020). "The hyperinsulinemia and lower insulin sensitivity observed in our study participants in the absence of overt hyperglycemia suggest that FGFR1 signaling may be temporally implicated in the early insulin hypersecretory phase and insulin resistance seen in initial stages of T2D pathophysiology." (PMID 38957656, 2024). "Gain and loss-of-function experiments identified a regulatory pathway in adipocytes involving miR-21a-3p, FGFR1, FGF21, and PPARγ that regulated adipocyte browning and participated in hyperglycemia-induced atrial fibrosis." (PMID 34484568, 2021). "In vivo and in vitro experiments demonstrated that PAL can significantly stimulate FGFR1 phosphorylation and upregulate glucose transporter type 1 (GLUT-1) expression, thereby facilitating glucose uptake in insulin resistance (IR) HepG2 cells as well as alleviating hyperglycemia in diabetic mice." (PMID 35935824, 2022).
Insulin resistance (9 papers, 2012 to 2025). Increased resistance towards insulin, that is, diminished effectiveness of insulin in reducing blood glucose levels. "In conclusion, using a genotype-first approach, we showed that FGFR1 human deleterious variants lead to insulin resistance and may increase the risk for T2D." (PMID 38957656, 2024). "While the inactivation of the FGFR1 signaling pathway worsened insulin resistance in this study, prior studies have shown the beneficial effect of the activation of the FGFR1 signaling pathway on the metabolic health of animals and humans." (PMID 38957656, 2024). "Therefore, digenic variants in FGFR1 and KLB provide a potential explanation for the subject’s severe insulin resistance and may represent a novel category of insulin resistance syndromes related to FGF21." (PMID 33210059, 2020). "We show that participants with rare heterozygous deleterious FGFR1 SNVs demonstrate higher insulin/C-peptide response to glucose and higher insulin resistance compared to noncarriers." (PMID 38957656, 2024). "Liraglutide treatment markedly improved insulin resistance and increased FGF-21 expression in liver and FGFR-3 in adipose tissue, restored β-Klotho mRNA expression in adipose tissue as well as FGFR-1-3, β-Klotho levels and phosphorylation of FGFR1 up to the levels observed in control mice in liver." (PMID 23152772, 2012).
mesenchymal tumors (9 papers, 2021 to 2026). "Clinically, phosphaturic mesenchymal tumors associated with FN1-FGFR1 fusion proteins cause increased FGFR1 signaling, resulting in ectopic FGF23 synthesis." (PMID 41473314, 2025). "The FN1::FGFR1 fusion gene is detected in phosphaturic mesenchymal tumors with paraneoplastic osteomalacia and FN1 has also been recently described as a novel fusion partner of ALK in an inflammatory myofibroblastic tumor." (PMID 36439507, 2022). "The FN1 gene may provide an oligomerization domain of its constituent active promoter and encoding protein to overexpress and promote the activation of the FGFR1 kinase domain in mesenchymal tumors." (PMID 34567847, 2021). "Molecular diagnosis identified a fibronectin 1- fibroblast growth factor receptor 1 (FN1-FGFR1) gene fusion, encountered in over 50% of cases of phosphaturic mesenchymal tumors, therefore confirming the diagnosis." (PMID 39888445, 2025). "Next-generation sequencing (NGS) showed an appreciable rise in FGFR1 and FGF23, affirming the diagnosis of a phosphaturic mesenchymal tumor." (PMID 39185431, 2024). "Half of phosphaturic mesenchymal tumors lack FGFR1 fusions; however, Klotho-β overexpression in this subset has suggested that in the absence of FGFR1 fusion, FGFR signaling is still active through Klotho-β." (PMID 34068954, 2021). "Thus, mutations in CAF markers such as Fibroblast growth factor receptor 1 (FGFR1) or PDGFRα, as well as consensus molecular subtypes 4 (CMS4) mesenchymal tumors are involved in resistance mechanisms to this therapy." (PMID 33800796, 2021).
mesothelioma (9 papers, 2009 to 2023). A usually malignant and aggressive neoplasm of the mesothelium which is often associated with exposure to asbestos. "For example, the PI3K/AKT signaling pathway regulating the cell cycle is aberrantly active in MPM, and the mesothelioma gene FGFR1 is connected to this pathway via its novel predicted PPIs with EIF4EBP1 and PRP2CB." (PMID 33916178, 2021). "Overexpression of FGF2 protein has been observed in primary mesothelioma tumor specimens, and both FGF2 and FGFR1 mRNA expression levels are high in mesothelioma compared to other tumor types in The Cancer Genome Atlas (TCGA) collection." (PMID 27223434, 2016). "This study also demonstrated that GSK3052230 is effective in inhibiting tumor growth of FGF2/FGFR1-overexpressing mesothelioma xenografts." (PMID 27223434, 2016). "Taken together, this data suggests that FGF autocrine signaling based on FGF2 and/or FGFR1 overexpression is important for mesothelioma cell proliferation." (PMID 27223434, 2016). "In line with this, it was shown that antiproliferative effects of the multikinase inhibitor sorafenib were most pronounced in tumor-initiating mesothelioma cells which expressed high levels of FGF2, leading to autocrine activation of FGFR1." (PMID 31527449, 2019). "Various studies have reported on the expression and activation of RTKs in mesothelioma, including EGFR, MET, IGFR, FGFR1, and VEGFR." (PMID 29755689, 2018). "Herein, the efficacy of this molecule was tested in models of mesothelioma, a tumor type shown to express high levels of FGF2 and FGFR1." (PMID 27223434, 2016). "Similarly, FGFR1 and its novel interactor NRG1 had elevated mRNA expression in H2722 mesothelioma cell lines and in MPM tissue, both contributing to increased cell growth under tumorigenic conditions." (PMID 33916178, 2021). "Specific inhibition of VEGFR, FGFR1, MET and/or EGFR suppressed mesothelioma cell growth in vitro." (PMID 29755689, 2018). "Similarly, FGF2 mRNA levels are highest in mesothelioma cell lines compared to all other cancer cell lines in the Cancer Cell Line Encyclopedia (CCLE), and FGFR1 expression is also high in these cells." (PMID 27223434, 2016). "In the mesothelioma cells we could detect a nuclear pool of syndecan-1 and FGF-2, whereas FGFR-1 remained exclusively perinuclear." (PMID 19802384, 2009). "Notably, there was no FGFR-1 reactivity present in the nucleus of mesothelioma cells." (PMID 19802384, 2009).
Apert syndrome (8 papers, 2012 to 2025). Apert syndrome (AS) is a frequent form of acrocephalosyndactyly, a group of inherited congenital malformation disorders, characterized by craniosynostosis, midface hypoplasia, and finger and toe anomalies and/or syndactyly. "The previous disease exhibits considerable overlap with Pfeiffer syndrome (MIM #101600) related to FGFR1 (MIM *136350) and FGFR2 variants and Apert syndrome (MIM #101200) related to FGFR2 variants." (PMID 40673520, 2025).
chronic eosinophilic leukemia (8 papers, 2013 to 2025). "The diagnosis of CNL also requires that molecular testing be negative for defining markers of alternate neoplasms including not only the BCR-ABL1 fusion gene but also rearrangements in PDGFRA/B or FGFR1, characteristic of eosinophilic leukemia." (PMID 29440636, 2018).
Crouzon syndrome (8 papers, 2013 to 2024). Crouzon disease is characterized by craniosynostosis and facial hypoplasia. "At the age of 5 she had the first genetic consultation at our clinic and on that occasion, following clinical suspicion of Crouzon syndrome, mutation screening of the FGFR1 and FGFR2 genes was performed through the dHPLC technique, with normal results." (PMID 35885943, 2022).